STAT1 (signal transducer and activator of transcription 1)
Diseases named in the same sentence as STAT1 in open-access papers (continued):
Sharing a sentence is not in itself a finding about the gene and the disease.
breast cancer (continued). "Moreover, all previous studies have been based on oncogene-driven mammary tumor formation in the absence of STAT1." (PMID 22185785, 2011). "Indeed, similar ECAR values were observed in breast cancer cells irrespective of whether they were treated with IFNγ or retained an intact STAT1 pathway." (PMID 34083537, 2021). "To further investigate this observation, we followed female mice lacking STAT1 longitudinally and found that they spontaneously develop ERα+/PR+, hormone-responsive mammary gland cancers of the luminal subtype, thus closely recapitulating the characteristics of human ERα+/PR+ luminal breast cancers." (PMID 22264274, 2012). "Finally, introduction of wildtype STAT1, but not a STAT1 mutant lacking the critical Tyr701 residue, into STAT1-/- mammary tumor cells results in apoptosis, demonstrating that the tumor suppressor function of STAT1 is cell-autonomous and requires its transcriptional activity." (PMID 22264274, 2012). "Although STAT1 and STAT2 are not hit genes by themselves, TFs from the STAT family have established connections to breast cancer and skin." (PMID 38632500, 2024). "MLKL mRNA expression correlated with IRF1 and STAT1 mRNA expression, but not with ESR1 expression, in breast cancer cell lines." (PMID 38474369, 2024). "Forced but transient expression of PTH-AS in PTH–nonexpressing T47D breast cancer cells did not induce PTH expression and upregulated STAT1 and its downstream IRDS genes." (PMID 35618021, 2022). "Although we do observe an inverse relationship between NQO1 and STAT1 levels in these breast cancer PDXs, the NQO1/STAT1 ratio is not sufficient to predict relative sensitivity to combined β-lapachone/phenformin treatment." (PMID 34083537, 2021). "Across 211 basal-like breast cancers, a statistically significant negative correlation was observed between Ras/MAPK and STAT1 activation." (PMID 33062958, 2020). "The mRNA levels of TGM2, SASH1, PARP9, STAT1 and ANXA1 were not significantly different between ER+ and ER--breast cancer tissues." (PMID 29416786, 2018). "High mRNA expression of STAT1 was not significantly related to OS (HR =0.94 (0.76–1.17), P=0.58) and PPS (HR =0.98 (0.77–1.25), P=0.87) in breast cancer patients." (PMID 29326301, 2018). "STAT1, but not STAT3, increased basal (MT/Shc313F/313F) and IFNγ-inducible (MT/ShcA+/+; MT/Shc2F/2F) surface MHC class I expression on breast cancer cells." (PMID 28276425, 2017). "Furthermore, STAT1-/- mammary tumor cells are transplantable orthotopically into both immunocompetent and immunodeficient mice, facilitating the examination of immune-based therapies, which otherwise would not be possible in xenograft models using ERα+/PR+ human breast cancer cell lines." (PMID 22264274, 2012). "STAT1 expression is known to be higher in the luminal (ER-positive) molecular subtype of breast cancer relative to HER2-positive or triple-negative breast disease, but we are not aware of any reports of its role in endocrine-resistant breast cancer." (PMID 24728078, 2014). "It has been reported that the abnormal expression of STAT1, ESR1, CYP1B1, FN1 and UGT1A family genes is closely related to breast cancer and TAM multidrug resistance, while the relationship between AKR1 family and breast cancer and TAM resistance has not been studied." (PMID 34886806, 2021). "In the breast cancer cell line MCF7, which does not originate from TNBC and was still able to respond to IFN treatment with reduced proliferation, the overexpression of IRF9, but not STAT1 or STAT2, increased the resistance of cells against the chemotherapeutic drug paclitaxel." (PMID 33430083, 2021).
melanoma (216 papers, 2003 to 2026). A malignant, usually aggressive tumor composed of atypical, neoplastic melanocytes. "To figure out the underlying mechanisms that STAT1 regulated melanoma resistance, we analyzed the correlation between STAT1 and epithelial-mesenchymal transition (EMT)." (PMID 40226609, 2025). "IFN-γ promotes tumorigenicity and metastasis in a syngeneic mouse model of melanoma, and this effect is STAT1-dependent and associated with the influence of IFN-γ on γδ T-cells." (PMID 40108693, 2025). "Our previous study showed that IFN-γ stimulated the binding between TET2 and STAT1 to activate target gene transcription, including those encoding chemokines, and we show here that in B16 melanoma cells INF-γ stimulates the interaction between TET2 and STAT1." (PMID 39388288, 2024). "This is the first report, to our knowledge, of increased survival associated with the nitration of a protein (e.g., STAT1) in melanoma." (PMID 36980641, 2023). "In contrast to the JAK1/2-deficient melanoma cells, STAT1 mutant cells were established from a treatment-naive stage III lymph node metastasis suggesting that in this case spontaneous anti-tumour T-cell responses enriched these cells." (PMID 28561041, 2017). "Accordingly, analyses on TCGA melanomas revealed a strong association between patient survival and elevated mRNA levels of STAT1 and its downstream target IRF1, indicating IFNγ-dependent pathway activation." (PMID 28561041, 2017). "Further analysis revealed that melanoma patients had a sub-optimal STAT1 activation response linked to lower IL-2-induced IFN-γ secretion in both CD56hi and CD56low NK cell subsets." (PMID 27153543, 2016). "The interaction of V and laboratory of genetics and physiology 2 or melanoma differentiation-associated gene 5 required for targeting STAT1 for degradation results in the inhibition of IFN signaling in chicken cells and Vero cells." (PMID 26975566, 2016). "The prophylactic application of the complex promoted antimetastatic immunity, leading to the autophagy-associated death of melanoma cells via IFNγ/STAT1 activation and attenuated tumor metastasis." (PMID 21931823, 2011). "We suspected that malfunction of STAT1 may increase the susceptibility of neutrophils switching to a protumor suntype in melanoma tumor microenvironment (TME)." (PMID 40226609, 2025). "Subgroup analyses revealed that the occurrence rate of STAT1 mutations in melanoma was 3.87%." (PMID 40226609, 2025). "Furthermore, an association of impaired STAT1 phosphorylation with the loss of IFN-mediated HLA class I induction was also found in melanoma cell lines." (PMID 37047709, 2023). "In addition, STAT1 was found to be strongly associated with overall survival in melanoma patients, where high STAT1 mRNA levels were associated with better survival outcomes." (PMID 37046994, 2023). "Its anti-tumor activity has been shown for fibrosarcoma and melanoma by the induction of HLA-I and signal transducer and activator of transcription 1 (STAT1)–associated cyclin-dependent kinase, leading to apoptosis of the tumor cells and recognition by the immune system." (PMID 35003017, 2021). "Moreover, a high (vs. low) expression of STAT1 is reported to be associated with a good prognosis in melanoma patients." (PMID 34282238, 2021). "Another research reported that the IFN-γ-induced activation of STAT1 could cause G1-arrest of melanoma cells through upregulating microRNA-29 family which target at CDK6." (PMID 33771156, 2021). "Mechanistically, STAT1KD predisposed human HNSCC and melanoma cells to RT-driven suppression of glycolysis and lactate dehydrogenase A (a key enzyme in glycolysis), suggesting that STAT1 can protect tumor cells from RT-induced deprivation of energy and cell killing." (PMID 34830176, 2021).
melanoma (continued). "In parallel, evaluation of primary resistance to anti-CTLA therapy in a cohort of 16 melanoma patients also revealed mutations in genes associated with IFNy signaling pathway in 12 patients, confirming that defects in the IFNy-STAT1 pathway provide resistance to immunotherapy." (PMID 31196219, 2019). "It was suggested that loss of MTAP expression in malignant melanomas might have an impact on therapeutic success by compromising tumor response to interferon treatment through its impact on STAT1 activity." (PMID 23816148, 2013). "In order to dissect the mechanism by which PTPN2 acts as an oncogene in melanoma and how its loss correlates with increased sensitivity of tumor cells to immunotherapy, it is important to underline that the tyrosine phosphatase inhibits IFNγ signaling by dephosphorylating STAT1 and JAK1." (PMID 33003469, 2020). "NO-producing MDSCs in tumor-bearing hosts would inhibit DC antigen presentation by inducing nitration of STAT1-Tyr701 in melanoma patients." (PMID 41535256, 2026). "Exemplary knockdown of NLRC5 and B2M by siRNA in three different melanoma cell lines confirmed that downregulation of the IFN-γ-induced STAT1 pathway indeed significantly impairs HLA-C expression and Vα3S1/Vβ13S1 TCR stimulation." (PMID 40243413, 2025). "When combined with IFN-γ at the cellular level or PD-1 inhibitors at the animal level, 6-MF expedited STAT1 phosphorylation and markedly activated the ferroptosis, resulting in oxidative ferroptosis in melanoma cells." (PMID 41347180, 2025). "Bufalin disrupts the ATP1A1-Cav-1 complex, reversing drug resistance in melanoma, while cardiac glycosides inhibit STAT1-mediated IDO1 expression, demonstrating synergy with immune checkpoint inhibitors." (PMID 40821775, 2025). "In a recent report, the first study to link Tan IIA induced ferroptosis with the STAT1/PTGS2 axis in melanoma was found." (PMID 40932870, 2025). "Concurrently, suppression of IFN-γ response genes (CXCL9, CXCL10, STAT1) mirrors observations in melanoma and lung cancer, where similar transcriptional silencing correlates with T cell exclusion and ICI resistance." (PMID 40873541, 2025). "Through network pharmacological analysis, the JAK/STAT signaling pathway was identified as a critical mechanism for melanoma treatment, with STAT1 highlighted as a key target." (PMID 40508400, 2025). "Western blot analysis confirmed MBP significantly inhibited the phosphorylation of JAK1 and STAT1 in melanoma cells." (PMID 40508400, 2025). "The inhibition of methyltransferase 3, N6-adenosine-methyltransferase complex catalytic subunit (METTL3) enhances the response to anti-PD-1 therapy in melanoma by stabilizing the IFN-γ/STAT1/IRF1 pathway." (PMID 40108693, 2025). "To see if these treatments also effect melanoma cells, we repeated the experiment with B16-F10 cells and observed a decrease in the activating phosphorylation sites of STAT1 and MHCII." (PMID 41429766, 2025). "Based on these findings, the role of the JAK1/STAT1 pathway in MBP-treated melanoma cells was experimentally validated by Western blot analysis." (PMID 40508400, 2025). "Survival analysis also disclosed that the differential expression of CXCL11, ICAM1, and STAT1 was accompanying through poor prognosis in progressive melanoma." (PMID 39820173, 2025). "In summary, constitutively expressed IκBζ in melanoma stabilizes specific promoter binding and chromatin association of STAT3, p65, and potentially STAT1, depending on the specific target gene." (PMID 40562773, 2025). "In melanoma, IFN-γ can induce tryptophan‐tRNA ligase (WARS), which is associated with STAT1, limiting the activity of IFN-γ/JAK/STAT signaling." (PMID 40108693, 2025). "The constitutive overexpression of STAT1 in melanoma cells promotes a pro-metastatic and therapy-resistant phenotype." (PMID 40508400, 2025). "As expect, treatment of Flu decreased the phosphorylation of STAT1 in neutrophils in B16-F10 melanoma tissue." (PMID 40226609, 2025).
melanoma (continued). "Among the 10 Treg.Sig genes, hub gene STAT1’s function was further validated in ICI resistance in melanoma mice receiving anti-PD-1 treatment." (PMID 40226609, 2025). "The results showed neutrophils expressed Arg-1 after cocultured with B16-F10 melanoma cells, and this trend was intensified while STAT1 was inhibited by Flu." (PMID 40226609, 2025). "Like IL6/STAT3, genetic and pharmacological targeting of GLI1 showed that IFNγ/STAT1 requires functional GLI as a second signal for the full-blown induction of IDO1 in human melanoma cells." (PMID 39962447, 2025). "Mechanistically, STAT1 impinged on ICI resistances by modulating the phenotypic switch in N2 neutrophil polarization in melanoma mice receiving anti-PD-1 therapy, which affects overall survival." (PMID 40226609, 2025). "Conversely, elevated STAT1 levels benefited long-term survival in patients with ovarian cancer, sarcoma, and melanoma." (PMID 40141028, 2025). "In this study, we demonstrate that myeloid-specific deletion of Rictor in a mouse melanoma model enhances STAT1 signaling while reducing PD-L1 expression." (PMID 41429766, 2025). "High expression of IFN-γ-related genes, including TBX21, STAT1, IRF1, and IFNG, is associated with better outcomes than anti-PD-1 monotherapy in melanoma patients." (PMID 40108693, 2025). "For example, melanomas often feature low levels of activated STAT1 and low APM expression as a result of upstream janus kinase (JAK) mutations." (PMID 38231444, 2024). "This enhancement occurs through the IFNG-signal transducer and activator of transcription 1 (STAT1)-interferon regulatory factor 1 (IRF1)-LPCAT3-induced ferroptosis pathway in mouse models of melanoma and lung cancer." (PMID 38844964, 2024). "It is notable that APM deficits in melanoma are often linked to JAK mutations, so downstream STAT1 remains intact and potentially capable of activating APM expression by other signaling pathways." (PMID 38231444, 2024). "miR-146a has a key role in the STAT1/IFNγ axis within the melanoma microenvironment, influencing melanoma cell migration, proliferation, mitochondrial function, and PD-L1 expression." (PMID 38462628, 2024). "We provide evidence that melanoma cells directly respond to IFNγ-activated STAT1 by increasing Nampt, which improves their fitness during tumor immunity." (PMID 36900204, 2023). "A cohort of patients with stage IIIC/IV melanoma was analyzed to examine the relationship between STAT1 post-translational modifications and RFS in response to anti-CTLA-4 adjuvant therapy." (PMID 36980641, 2023). "Here, sustained INHBA expression or acute treatment of YUMM3.3 melanoma cells with recombinant Activin-A enhanced STAT1 phosphorylation by IFN-γ but interfered with cytostatic IFN-γ signaling in vitro without further upregulating IFN target genes." (PMID 38304252, 2023). "Overall, based on the RNA-seq results for melanoma tumor tissues, we concluded that α-KG promotes IFNγ-STAT1/3-CD274 signaling through TET2/3, which in turn improves immune responsiveness and ultimately enhances the therapeutic efficacy of anti-PD1 therapy." (PMID 36854755, 2023). "At present, some studies have confirmed that some kinds of cancer cells, including melanoma, squamous cell carcinoma and gastric carcinoma, can achieve the purpose of immune escape by downregulation of STAT1 expression." (PMID 36524848, 2023). "Phosphoflow cytometry was used to analyze p-STAT1 expression in PBMCs from 17 healthy donors and 19 melanoma patients before and after treatment with IFN-α." (PMID 37741983, 2023). "Module M2 contained the STAT1 regulator, which has been linked to C4 Melanoma CORO1A, C0 Melanoma BIRC7, and C6 Melanoma GJB2." (PMID 37435067, 2023). "CXCL10 and STAT1 have also been suggested as key candidate genes for understanding the molecular mechanism of melanoma." (PMID 37048082, 2023).
melanoma (continued). "Further emphasizing an intersection with IFN signaling, Activin-A also modulated an IFN-γ response within these melanoma cells in vitro, as shown by increased STAT1 phosphorylation accompanied by a marked attenuation of IFN-γ induced cytostasis." (PMID 38304252, 2023). "NRIR, firstly found to be associated with melanoma by our study, was positively correlated with CYLD, MLKL, STAT1, and TNFSF10." (PMID 37147395, 2023). "This study identified that the signal transducer and activator of transcription 1 (STAT1) protein, which must be phosphorylated at Tyrosine 701 during DC antigen presentation, is instead nitrated at Tyrosine 701 in patients with melanoma or pancreatic cancer." (PMID 37830618, 2023). "Healthy donors had higher basal levels of p-STAT1 in total PBMCs, NK cells, and T cells compared to melanoma patients." (PMID 37741983, 2023). "FLLL32, a structural analog of curcumin, specifically inhibits STAT3 while retaining STAT1 mediated signal transduction within melanoma and immune-sensitive cells." (PMID 35401182, 2022). "Since the IFN-γ signaling pathway in melanoma cells induces tumor growth arrest and death, mutations of IFNGR1, IFNGR2, JAK1, JAK2, STAT1, and IRF3 lead to insensitivity to anti-tumor IFN-γ activity." (PMID 35432377, 2022). "Both STAT1 mRNAs isoforms shifted from heavy polysome fractions to lighter polysome fractions upon silvestrol treatment, indicating that silvestrol inhibits the translation of both STAT1 mRNA isoforms in activated T cells, as observed above in melanoma cells." (PMID 35267483, 2022). "In previous studies, it was reported that IFNs secreted by T cells activate STAT1 to increase the expression of PD-L1 in chronic hepatitis, melanoma and gastric carcinoma." (PMID 35927628, 2022). "We recently showed that, in interferon-γ-treated melanoma cells, translation of the signal transducer and activator of transcription 1 (STAT1) transcription factor is upregulated in an eIF4F-dependent manner, leading to transcriptional upregulation of PD-L1." (PMID 35267483, 2022). "In the mouse melanoma model, miRNA-146a is regulated by STAT1 and STAT1 cytokine interferon-γ, reducing cell migration, cell cycle activity, and oxygen consumption." (PMID 36377198, 2022). "To establish the role of STAT1 in this pathway within melanoma, we developed a STAT1-centered network model from pSKCM, and intersected it with STAT1 perturbation signature in the Stat1-KO mouse model from bone-marrow-derived macrophages (BMM)." (PMID 33619278, 2021). "It has been reported that chronic exposure to IFNs reprogrammed the epigenome in melanoma cells via STAT1-dependent signaling." (PMID 34771447, 2021). "A functional antagonism between STAT1 and STAT5 has been identified in melanoma cells with STAT1 able to inhibit, and STAT5 able to promote tumor growth." (PMID 34571790, 2021). "In melanoma and lung cancer models, impaired phosphorylation of STAT1 in response to IFN-γ results in low MHC induction rate and reduced IFN-γ sensitivity due to defective JAK signal transduction." (PMID 34215720, 2021). "It has been shown that the STAT1 protein is nitrated by nitric oxide (NO) derived from MDSCs during melanoma and pancreatic cancer, causing a disruption of the JAK/STAT1 signaling pathway." (PMID 34299314, 2021). "NK cells from melanoma patients showed impaired activation of STAT1, a critical molecule in the IFNγ-mediated signaling pathway, after IL2 stimulation." (PMID 33809795, 2021). "Regarding its immunologic function, we suggest that STAT1 is widely involved in melanoma immune responses in a complex way." (PMID 33511023, 2021). "Chronic exposure to IFNs has been observed to reprogram melanoma cells via a STAT1-dependent mechanism." (PMID 34771447, 2021). "We report herein that vemurafenib downregulates IFN‐γ‐induced PD‐L1 expression in melanoma cells by interfering with the STAT1 activity and by decreasing PD‐L1 protein translation." (PMID 32330348, 2020).